BTBD2 (BTB domain containing 2)
Tractability: PROTAC: ubiquitination databases record sites on it.
Gene: Protein-coding gene on chromosome 19 (1,985,438 to 2,034,881, reverse strand). Ensembl gene ENSG00000133243.
Subcellular location: Cytoplasm
Gene Ontology:
Molecular function: protein binding
Biological process: neurogenesis
Cellular component: cytoplasm; cytoplasmic ribonucleoprotein granule; cytosol; P-body
Genetic constraint (gnomAD): Loss-of-function variants: 15 observed, 36.36 expected, observed/expected ratio (o/e) 0.41, 90% interval 0.28 to 0.63. The synonymous counts are far from expectation, so gnomAD's model fits this gene poorly and the ratio says little. Missense variants: 582 observed, 628.9 expected, observed/expected ratio (o/e) 0.93, 90% interval 0.86 to 0.99. Synonymous variants: 394 observed, 282.79 expected, observed/expected ratio (o/e) 1.39, 90% interval 1.28 to 1.51.
Homologues: Orthologues: pig BTBD2 (90% identical), dog BTBD2 (89% identical), mouse Btbd2 (86% identical), rat Btbd2 (86% identical), chimpanzee BTBD2 (85% identical), guinea pig BTBD2 (84% identical), tropical clawed frog btbd2 (81% identical), zebrafish btbd2a (79% identical), zebrafish btbd2b (78% identical), Drosophila melanogaster lute (42% identical), Drosophila melanogaster CG17068 (26% identical), Drosophila melanogaster BTBD9 (18% identical), and 1 more. Paralogues in human: BTBD1 (71% identical), BTBD6 (42% identical), BTBD3 (40% identical), ABTB3 (21% identical), BTBD9 (20% identical), ABTB2 (19% identical), KBTBD4 (16% identical), ABTB1 (14% identical), SPOP (14% identical), SPOPL (14% identical), KLHL11 (9% identical).
Diseases named in the same sentence as BTBD2 in open-access papers:
BTBD2 is named in the same sentence as 5 diseases in open-access papers, as found by Europe PMC text mining. Sharing a sentence is not in itself a finding about the gene and the disease. The quoted sentences say what the papers report.
Batten’s Disease (1 paper, 2025). "Other proteins enriched in UBQLN24XALS IPs included BTBD2, which encodes a Ub E3 ligase involved in cytoskeletal dynamics and Top1-mediated chromatin relaxation, and phospholipase B D2 (PLBD2), a lysosomal phospholipase that has been implicated in the lysosomal storage disorder, Batten’s Disease." (PMID 41561437, 2025).
HIV-1 infection (1 paper, 2010). The type species of lentivirus and the etiologic agent of acquired immunodeficiency syndrome (AIDS). "We also found that depletion of BTBD2 in COS-1 cells increased their permissiveness to HIV-1 infection by 2.5 to 3-fold." (PMID 21092135, 2010). "Cells transfected with the BTBD2 shRNA plasmid were 2.5 to 3-fold more permissive to HIV-1 infection." (PMID 21092135, 2010). "We next evaluated the effect of the BTBD1 and BTBD2 shRNA plasmids transfected individually on permissiveness to HIV-1 infection in COS-1 cells." (PMID 21092135, 2010). "Our data show that in both human and AGM cells, depletion of BTBD2 only modestly increased permissiveness to HIV-1 infection by about 2-3 fold." (PMID 21092135, 2010). "Similar to their results, siRNA targeting TRIM5 increased permissiveness to HIV-1 infection up to 20 fold, which is roughly eight-fold more permissiveness than we observed in AGM cells transfected with the BTBD2 shRNA plasmid." (PMID 21092135, 2010). "Additionally, interference with the expression of BTBD2 in AGM and human 293T target cells increased their permissiveness to HIV-1 infection two- to three-fold." (PMID 21092135, 2010). "We also show that interference with the expression of BTBD2 modestly increases HIV-1 infection in both non-permissive AGM cells and permissive 293T cells." (PMID 21092135, 2010).
cancer (2 papers, 2013 to 2020). A tumor composed of atypical neoplastic, often pleomorphic cells that invade other tissues. "In BTBD2-TEP1, TEP1 is a well-known GBM suppressor gene, and the deletion/mutation of this gene has been observed in many cancers, including GBM; polymorphism of BTBD2 is involved in the double-strand break repair pathway that can be useful for GBM survival." (PMID 23940583, 2013). "In BTBD2-BARD1, BARD1 was suggested as a mediator of apoptosis since its over-expression induces cell death; and high LOH has been detected in human carcinoma metastases to the brain at chromosome 19p13.3 for BTBD2." (PMID 23940583, 2013). "Moreover, by comparing the 13 survival-related gene lists, seven genes (SLK, API5, BTBD2, PTAR1, VPS37A, EIF2B1, and ZRANB1) were found to be associated with prognosis in a variety of cancers." (PMID 32300588, 2020).
infection (1 paper, 2010). The state of being infected such as from the introduction of a foreign agent such as serum, vaccine, antigenic substance or organism. "Similarly, in human embryonic kidney 293T cells, depletion of BTBD2 increased permissiveness to infection by 1.8 to 2.8-fold (data not shown)." (PMID 21092135, 2010).
BTBD2 also shares sentences with these, for which no sentence is quoted: lysosomal storage disorder (1 paper).